PGR (progesterone receptor)
Diseases named in the same sentence as PGR in open-access papers (continued):
Sharing a sentence is not in itself a finding about the gene and the disease.
breast cancer (continued). "In our cohort, MMR deficiency was present across all major breast cancer subtypes, and was associated with high-grade, low-progesterone receptor expression and high tumor-infiltrating lymphocyte counts." (PMID 31522348, 2020). "The present study aims to find the expression of ER and PgR in breast carcinoma and its association with prognostically important clinicopathological variables." (PMID 32944466, 2020). "High p16 expression in breast carcinoma correlates with unfavorable prognostic factors such as poor overall survival, poor disease-free survival, ER (estrogen receptor) and PR (progesterone receptor) negativity and an increased risk of relapse cancer." (PMID 32178642, 2020). "Recurrence and metastasis are the two leading causes of death in breast cancer, especially in Oestrogen receptor (ER), progesterone receptor (PR) and human epidermal growth factor receptor 2 (HER2) triple-negative breast cancer (TNBC)." (PMID 30992017, 2019). "Dietary lignan consumption has been found to be associated with reduced risk of postmenopausal breast cancer specifically in ER and progesterone receptor-positive cases, suggesting that these compounds are acting through an ER related mechanism." (PMID 30908519, 2019). "Apart from haplotypes of EPCR, a single nucleotide polymorphism (SNP) of EPCR, rs2069948, was associated with estrogen receptor (ER) and progesterone receptor (PR) positivity in breast cancer specimens." (PMID 30626007, 2019). "Increased estradiol level is associated with breast cancer development through regulation of the progesterone receptor." (PMID 31311202, 2019). "In the TCGA BRCA data, our model identified that around 31.9% genes were best fitted by either the MG or LTMG model with more than one peaks, such as the ESR1 and PGR genes that are associated with the breast cancer subtype." (PMID 31861972, 2019). "Increased WBP2, which functions as the transcriptional coactivator of ERα/progesterone receptor (PR) transactivation, was associated with poor prognosis in ER+ breast cancer patients." (PMID 31590453, 2019). "One report stated that messenger ribonucleic (mRNA) expression of CRABP2 in breast cancer is associated to the status of ER, progesterone receptor (PR), and human epidermal growth factor receptor 2 (Her2)." (PMID 31419991, 2019). "In particular, despite that high intake of β-carotene reduces the risk of many cancers, the effect on breast cancer risk depends on estrogen receptor (ER) and progesterone receptor (PR) statuses." (PMID 29861829, 2018). "We investigated the relationship between nut intake and risk of postmenopausal breast cancer, and estrogen/progesterone receptor (ER/PR) subtypes." (PMID 29168062, 2018). "Our meta-analysis included 10 studies, comprised of 2106 cases and 1660 controls, that investigated the association between PGR gene polymorphism (specifically, the Alu insertion) and the occurrence of breast cancer." (PMID 29370776, 2018). "For breast cancer, one study associated this SNP with some histopathological features such as progesterone receptor status." (PMID 28596490, 2017). "Multiple studies have documented an association between alcohol intake and increased risk of ER+ and/or estrogen receptor and progesterone receptor-positive (ER+/PR+) breast cancer." (PMID 28805741, 2017). "While associations between PgR gene polymorphisms and breast cancer have been well-studied, results remain inconsistent." (PMID 29084518, 2017). "In the diagnostic evaluation of breast cancer, estrogen receptor (ER), progesterone receptor (PgR), human epidermal growth factor receptor 2 (HER2) and Ki-67 are routinely used for the classification of breast tumors into distinct subtypes." (PMID 28356061, 2017). "This meta-analysis included 12,453 breast cancer cases and 14,056 controls, and was used to evaluate reported associations between breast cancer risk and the +331G/A (rs10895068) functional polymorphism in the PgR gene promoter." (PMID 29084518, 2017).
breast cancer (continued). "Recent meta-analyses have established that adult body size has a differential effect on breast cancer according to estrogen and progesterone receptor (ER/PR) status, for example, increased risk of ER+/PR+ tumors." (PMID 28732505, 2017). "In this work breast cancer interactions with clock gene polymorphisms were stratified by work conditions, menopausal status and tumor estrogen receptor/progesterone receptor expression." (PMID 28177907, 2017). "Other prognostic and predictive markers include estrogen receptor (ER)/progesterone receptor (PR)/human epidermal growth factor receptor 2 (HER2) for breast cancer, KRAS mutation for colon cancer, and anaplastic lymphoma kinase (ALK) mutation for lung cancer." (PMID 28335509, 2017). "We identified ER and PgR expression loss in 17% and 41% of cases, respectively, across the relapsed breast cancer cohort." (PMID 28810143, 2017). "Of note, hormone-dependent regulation of GGH is also supported by a recent study showing strong associations of GGH and estrogen/progesterone receptor levels in breast cancer." (PMID 28146062, 2017). "These advantages allowed us to more precisely assess the + 331G/A PgR gene polymorphism and breast cancer risk associations than previous meta-analyses." (PMID 29084518, 2017). "The breast cancer subgroup was further stratified by work conditions, estrogen receptor/progesterone receptor status and menopausal status, conditions associated with the risk of breast cancer in different studies." (PMID 28177907, 2017). "Many published studies have estimated the association between the +331G/A (rs10895068) polymorphism in the progesterone receptor (PgR) gene and breast cancer risk." (PMID 29084518, 2017). "Our summary results indicate that an association is indeed present between PgR +331G > A and the risk of breast cancer." (PMID 29084518, 2017). "Regarding the clinicopathological features, in our series of breast cancers, mNHERF1 expression was positively associated with favourable clinicopathological features, such as ER-positivity, PgR-positivity and low proliferative activity." (PMID 29029467, 2017). "Fulvestrant is a novel hormone receptor antagonist that causes rapid degradation of both the ER and the progesterone receptor (PgR) and has been shown to be highly effective for treating late stage breast cancer." (PMID 28615518, 2017). "We performed the online search of multiple databases for available studies reporting associations between PgR +331G/A polymorphisms and breast cancer risk." (PMID 29084518, 2017). "Among ERα+ tumor types, loss of PGR expression correlates with aberrant estrogen signaling, and we show that AGO2 expression in an ERα+ breast cancer cell line can repress classical ERα signaling (loss of ERα expression and loss of E2 stimulation of PGR)." (PMID 29657266, 2016). "Currently, common risk factors for distant metastasis of breast cancer include tumor size, nodal stage, histological grade, estrogen receptor (ER), progesterone receptor (PR), human epidermal growth factor receptor 2 (HER2), and others." (PMID 27322074, 2016). "Recently, PgR expression < 20 % has been associated with poor prognosis, and patients initially diagnosed with PgR+ breast cancer had a worse outcome if recurrence of disease was PgR−." (PMID 26970778, 2016). "A pooled analysis of 18 prospective cohort studies reported in 2012 for evaluating carotenoid intakes and breast cancer risk defined by estrogen receptor (ER) and progesterone receptor (PR) statuses by using the “highest versus lowest intake” method (HLM)." (PMID 27283141, 2016). "The G allele of rs2291738 and the C-allele of rs7302060 are associated with reduced risk of breast cancer among estrogen receptor (−) or progesterone receptor (−) positive breast cancer cases (OR, 0.46 and 0.36, resp)." (PMID 27313610, 2016).
breast cancer (continued). "Loss of PgR expression in ER-positive (ER+) breast cancer potentially defines a subgroup with impaired function in the ER pathway, which probably gains limited benefit from endocrine therapy." (PMID 26437901, 2015). "An association of obesity and progesterone receptor positivity in mammary tumors has recently been demonstrated in an in vivo obesity and overfeeding rat model conducted in the MacLean laboratory." (PMID 25866757, 2015). "Alcohol-associated breast cancers tend to be estrogen receptor (ER)-positive and progesterone receptor (PR)-positive." (PMID 26661278, 2015). "Many theories have previously been proposed to explain the biology of PgR loss in ER+ breast cancer." (PMID 25938238, 2015). "Gene cluster B contained ERα and a group of NRs previously associated with ERα in breast cancer, including PGR, AR, RARα, LRH-1, PNR, as well as TRβ, RORβ, and RORγ." (PMID 26280373, 2015). "The majority of ER−/PgR+/HER2– phenotype breast cancers are basal-like and associated with a lower endocrine therapy sensitivity score." (PMID 26437901, 2015). "Our previous studies had shown that ORAI1 is an associated gene to breast cancer with the nodal involvement, progesterone receptor status, and estrogen receptor status studies." (PMID 26380267, 2015). "More than 70% of breast carcinomas are estrogen receptor (ER) and progesterone receptor (PR) positive and are thus potentially susceptible to anti-endocrine therapies." (PMID 26098779, 2015). "The ovarian steroid hormone, progesterone, and its nuclear receptor, the progesterone receptor, are implicated in the progression of breast cancer." (PMID 24552158, 2014). "CST6 loss in breast cancers has been shown to be associated with loss of both ERα and the progesterone receptor." (PMID 24742492, 2014). "The clinical, pathologic, and molecular characteristics of breast cancer differ by their ER and/or PGR expression profile and the effects of risk factors of breast cancer, such as reproduction related exposures, also differ by ER/PGR status." (PMID 24963789, 2014). "Loss of estrogen and progesterone receptor gene expression has been found in 30% of human breast cancers, and this condition is associated with less differentiated tumors and poor clinical outcome." (PMID 25230850, 2014). "Recent studies identified an oxidant-sensitive subset of estrogen/ER-responsive breast cancer genes linked to cell growth and invasion pathways that was associated with loss of progesterone receptor and earlier disease-specific mortality." (PMID 25011585, 2014). "The luminal B breast cancer subtype is classified as ERα+; however, altered ER signaling is commonly observed along with loss of PgR expression." (PMID 25283550, 2014). "For breast cancer, risk analyses were also carried out for estrogen receptor classification (ER+ and ER-), progesterone receptor classification (PGR+ and PGR-) and for the two most frequent histology types (ductal and lobular)." (PMID 24963789, 2014). "Estrogen-α and progesterone-receptor (ER and PR) expression is routinely used to determine the prognosis of human breast cancers, expression loss being associated with poor prognosis." (PMID 25230850, 2014). "As AMPKα expression was significantly associated with ER, PgR and basal-phenotype status, we further investigated the prognostic significance of AMPKα expression in different subtypes of breast cancer in the validation cohort." (PMID 25427448, 2014). "This case-control study investigated the association of cigarette smoking with breast cancer risk in terms of estrogen-receptor/progesterone-receptor (ER/PgR) status." (PMID 24516791, 2014). "Molecular markers such as progesterone receptor, estrogen receptor, and ErbB2 have been associated with the five major subtypes of breast cancer: luminal A, luminal B, ErbB2+/ER-, basal-like, and normal breast-like." (PMID 24628760, 2014).
breast cancer (continued). "Multiple studies of Western populations have suggested that excess endogenous estrogen due to obesity contributes to an increased risk of both estrogen receptor (ER) and progesterone receptor (PR) positive breast cancer in post-menopausal women." (PMID 24489874, 2014). "The immunohistochemical detection of estrogen receptor (ER) and progesterone receptor (PR) is an indispensable part of the routine workup of breast cancer in diagnostic pathology providing critical prognostic information, and guiding clinical decisions." (PMID 25565114, 2014). "For this data set, we sought to identify pathways linked with estrogen receptor (ER) and progesterone receptor (PGR) activity in breast cancer." (PMID 25213199, 2014). "Previous studies have shown loss of PgR expression in clinical samples is used as an indicator of aberrant growth factor signaling and the IGF induced AKT/mTOR signaling pathway is commonly associated with the repression of PgR in breast cancer systems." (PMID 25283550, 2014). "Alterations in these processes are common to many tumors, but transcripts associated with breast cancer subtypes, like estrogen- or progesterone receptor controlled lncRNAs, are likely underrepresented on the array." (PMID 25264628, 2014). "Clinical management of breast cancer is currently based on diagnostic evaluation of expression of estrogen receptor (ER), progesterone receptor (PR) and HER2." (PMID 24520381, 2014). "Loss of PGR expression is often considered as a marker for the gain of hormone-independent growth properties by ERα-positive breast cancers, through increased cross-talk between ERα and growth factor signaling pathways." (PMID 24758297, 2014). "Taken together, our data demonstrate a role for a miR-155-mTOR-ERα signaling axis in the progression of breast carcinomas towards a hormone independent phenotype evident through the loss of PgR." (PMID 25283550, 2014). "The rs362962 TT genotype also associated with risk of estrogen receptor or progesterone receptor positive breast cancer." (PMID 23922822, 2013). "Breast cancers with lactating features, some of which are associated with pregnancy and lactation, are often poorly differentiated, lack estrogen receptor, progesterone receptor, and HER2 expression and have high mortality." (PMID 23596564, 2013). "In previous published pooled studies, Yang and colleagues have reported an association between PgR +331 G/A variant and breast cancer risk." (PMID 23349706, 2013). "In any case, the association of the evolutionarily more recent ABCB1 T-alleles in the SNPs examined with PgR- and ER-positivity in breast carcinomas is a novel finding meriting further investigation." (PMID 23935969, 2013). "Examination of specific estrogen receptor (ER) or progesterone receptor (PR) types in the major sectors showing excess breast cancer produced distinct associations across receptor types." (PMID 23164221, 2012). "Lower BMI is associated with higher all-cause and breast cancer-specific death in patients with ER + or PgR + tumors." (PMID 22510365, 2012). "Various proteins are established as diagnostic and prognostic biomarkers in breast cancer, including estrogen and progesterone receptor status, human epidermal growth factor receptor 2 (HER2) and E-Cadherin." (PMID 22792263, 2012). "TNBC is the most frequent phenotype associated with basal-like molecular subtype of breast cancer characterized mainly by ERα, PgR, and HER2 absence." (PMID 22439831, 2012). "Analysis stratified according to hormonal receptor status showed that higher and lower BMI were associated with increased risks of all-cause and breast cancer-specific death only for patients with ER + or PgR + tumors." (PMID 22510365, 2012). "Heavier women (≥25.8 kg/m2) with ER + or PgR + tumors showed a higher risk of breast cancer-specific death (4.95, 1.05–23.35)." (PMID 22510365, 2012).
breast cancer (continued). "Among women with ER + or PgR + tumors, BMI was significantly associated with both all-cause (multivariate-adjusted p for trend = 0.02) and breast cancer-specific death (multivariate-adjusted p for trend = 0.031) if the women had a BMI of ≥21.2 kg/m2." (PMID 22510365, 2012). "Among post-menopausal women, however, an elevated BMI has been positively associated with the development of breast cancer, particularly in the cases of estrogen receptor-positive (ER+) and progesterone receptor-positive (PR+) tumors." (PMID 23061041, 2012). "In conclusion, being obese is a risk factor for all-cause death in premenopausal women and a risk factor for all-cause and breast cancer-specific death in patients with ER + or PgR + tumors." (PMID 22510365, 2012). "If this hormonal environment of the post delivery period influences the risk of breast cancer, it should be restricted to ER/PgR-positive cancers." (PMID 22711317, 2012). "Our present multivariate-adjusted analysis showed that BMI <21.2 kg/m2, i.e. low BMI, was associated with elevated risks of both all-cause and breast cancer-specific death among women with ER + or PgR + tumors." (PMID 22510365, 2012). "Clinical markers including estrogen receptor (ER), progesterone receptor (PR) and tumor grade have long been used to classify breast cancer subtypes associated with differential prognosis and response to cancer therapy." (PMID 21386992, 2011). "In our set of breast carcinomas stromal expression of zeb 1 was associated with the estrogen and progesterone receptor status of the tumors." (PMID 21324165, 2011). "Studies on large series of BRCA2-associated breast cancers indicate that these tumours are predominantly high-grade IDCs of no special marker subtype, and that they are more often oestrogen- and progesterone-receptor positive." (PMID 20877358, 2010). "Lastly and most importantly methylation of EMILIN2 was associated with poorer clinical outcome in breast cancer and was strongly associated with estrogen receptor as well as progesterone receptor positive breast cancers." (PMID 20205715, 2010). "Multivariate analysis with a Cox model demonstrated that tumour stage and progesterone receptor-status were significantly and independently associated with relapse-free survival in patients with breast cancer." (PMID 21129170, 2010). "Immunohistochemical staining of the estrogen receptor (ER), progesterone receptor (PR), and proliferation antigen Ki-67 are routinely used in the diagnostic assessment of breast cancer." (PMID 20663194, 2010). "A secondary aim was to evaluate these interactions in susceptibility to breast cancer subtypes defined by ER and progesterone receptor (PR) status." (PMID 21194473, 2010). "Progesterone receptor is a fundamental orchestrator of breast development and function, but is also implicated in breast cancer development and progression, although its role in these processes is still to be fully established." (PMID 18665217, 2008). "In the Iowa Women's Study enhanced physical activity level was associated with decreased risks of ER-positive/progesterone receptor (PR)-positive, ER-positive/PR-negative and ER-negative/PR-negative breast cancers." (PMID 18976449, 2008). "Studies of the possible association of genetic variation in progesterone receptor polymorphism with risk of ovarian and breast cancer have concentrated on a variant known as PROGINS." (PMID 17919323, 2007). "It has been suggested that hormonal risk factors act predominantly on estrogen receptor and progesterone receptor (ER/PR)-positive breast cancers." (PMID 16846528, 2006). "One way of confirming this would be to use more specific antibodies to determine the ratios of the two PgR isoforms in the breast epithelium from the mutation carriers compared to those from subjects at population risk of breast cancer." (PMID 16538216, 2006).